FKBP5 (FKBP prolyl isomerase 5)
Diseases named in the same sentence as FKBP5 in open-access papers (continued):
Sharing a sentence is not in itself a finding about the gene and the disease.
depression (continued). "The FKBP5 gene has been associated with high rates of depression or other mental illnesses." (PMID 40869374, 2025). "DNA methylation patterns may have value in predicting antidepressant response; for example, altered FKBP5 methylation is associated with both depression severity and SSRI responsiveness." (PMID 41589304, 2025). "FKBP5 has consistently been linked to stress-related disorders in humans, with elevated levels correlating with amplified stress sensitivity and greater susceptibility to depression." (PMID 39438757, 2025). "Additionally, common allelic variants within the FKBP5 gene are linked to increased susceptibility to MDs such as depression, anxiety, and PTSD." (PMID 38786025, 2024). "Moreover, FKBP5 polymorphism is associated with anxiety and depression in patients with advanced gastric cancer." (PMID 38995968, 2024). "In addition, GR target gene FKBP5 is implicated in depression, as its polymorphisms are associated with HPA axis parameters, response to antidepressant treatment, and recurrence of depressive episodes." (PMID 38916735, 2024). "Interestingly, the FKBP5 moderation of GR response exerted by variants associated with depression was also more prominent in astrocytes than neurons." (PMID 39361217, 2024). "While these 21 studies all investigate FKBP5 gene polymorphisms in relation to genetic susceptibility and treatment response to depression, substantial heterogeneity exists in terms of study subjects, design, depression typing, assessment criteria, and antidepressant type." (PMID 38609904, 2024). "However, there are no consistent findings regarding the haplotype distribution of FKBP5 gene SNPs and their association with depression susceptibility and antidepressant treatment response in other studies." (PMID 38609904, 2024). "Although FKBP5 has been associated with a variety of psychiatric disorders, whether FKBP5 influences depression susceptibility in MAUD is unknown so far." (PMID 37051166, 2023). "FKBP5 is involved in regulating glucocorticoid receptor (GR) sensitivity, and GR resistance and associated stress hormone dysregulation are among the strongest biological findings in severe depression." (PMID 38249586, 2023). "We hypothesized that the tested FKBP5 polymorphisms have significant associations with FS, independent from their comorbid depression." (PMID 36825897, 2023). "Our hypothesis is that OHRQoL, feelings of happiness, and polymorphisms in candidate genes, such as COMT, HTR2A and FKBP5, could be associated with anxiety, depression and chronic pain." (PMID 36834016, 2023). "FKBP5 genetic variants have been previously reported to confer the risk of depression and PTSD." (PMID 37274192, 2023). "A systematic review provided strong evidence of interactions between FKBP5 genotypes and early-life stress, which could pose a significant risk for stress-associated neuropsychological disorders (e.g., depression and PTSD)." (PMID 37628589, 2023). "Importantly, sex-dependent differences in the interaction of FKBP5 and life adversities have been associated to a higher prevalence of depression in females." (PMID 35449298, 2022). "Studies of FKBP5 show support for a significant association between reduced DNA methylation and increased risk of psychiatric disorders among adults, such as post-traumatic stress disorder and depression." (PMID 36451133, 2022). "The overall associations between FKBP5 and depression confirm previous findings." (PMID 34423378, 2021). "Prior evidence has shown that alteration in DNA methylation of the FKBP5 gene may be associated with mental disorders such as depression or depressive symptoms, which remains to be studied." (PMID 34753443, 2021). "However, in line with the present findings, several studies reported an association of the major alleles of FKBP5 SNPs with depression, suicidal events in depressed patients, and more depressive symptoms in male adolescents in the context of victimization." (PMID 32860562, 2020).
depression (continued). "Moreover, a SNP in the FKBP5 gene has been associated with susceptibility to develop depression after childhood physical abuse." (PMID 31740756, 2020). "Our findings suggest that the exact characteristics of stressors occuring in adulthood might be central for the FKBP5 × stressor interaction on risk for depression or possibly also other stress-related psychiatric disorders." (PMID 32860562, 2020). "Another interpretation might be that FKBP5 is a pleiotropic gene increasing the risk for both depression and CHD." (PMID 32860562, 2020). "Further research will have to unravel the nature of FKBP5 × adult stress interactions and to investigate whether determining FKBP5 genotype might aid in identifying CHD patients at risk for categorical clinical depression." (PMID 32860562, 2020). "Finally, we evaluated the moderating effects of rs1360780, a SNP located in intron 2 of the FKBP5 gene, for which the most consistent findings on depression risk and antidepressant treatment outcome have been reported." (PMID 30678080, 2019). "Finally, we analyzed the moderating effects of rs1360780, a single nucleotide polymorphism (SNP) located in intron 2 of the FKBP5 gene, for which the most consistent findings on depression risk and antidepressant treatment outcome have been reported." (PMID 30678080, 2019). "Additional FKBP5 SNPs have been implicated in depression, PTSD, and exposure to childhood trauma." (PMID 30619472, 2018). "As can be seen, the vast majority of studies have focused on associations between depression and the FKBP5 genotype by investigating multiple single nucleotide polymorphisms (SNPs) throughout the gene (with a particular focus on the initially reported rs1360780)." (PMID 29206196, 2017). "Several studies have demonstrated that FKBP5 is associated with major depression and chronic pain." (PMID 28579944, 2017). "Furthermore, mutations in genetic regions involved in abnormal HPA-axis function (such as the FKBP5 allele) have also been associated with an increased risk for depression, and are similarly associated with abnormal plasma cortisol and ACTH concentrations." (PMID 27199779, 2016). "FKBP5 has been strongly implicated in depression pathology, so future studies should investigate whether FKBP5 polymorphisms are also significant modifiers for depression within the AD patient population." (PMID 25806005, 2015). "Since the initial discovery of the association between FKBP5 SNPs and depression, other psychiatric disorders have been found to be associated with FKBP5 SNPs including PTSD, bipolar disorder, anxiety, peritraumatic dissociation, and major depression in HIV patients." (PMID 21935478, 2011). "Given the differences of LD between the promoter region and distal areas, different genetic variants may be relevant at FKBP5 in depression." (PMID 17081296, 2006). "Determining the impact of polymorphisms in the FKBP5 gene on genetic susceptibility to depression and their influence on the response to antidepressant medication could enable the prediction of treatment effectiveness and medication side effects for a patient prior to initiating treatment." (PMID 38609904, 2024). "For instance, the short allele of 5-HTTLPR was associated with increased risk for major depressive disorder in women and stressful life events could enhance the effect; and female carriers of minor allele of rs1360780 in FKBP5 displayed more depressive symptoms under high external stress." (PMID 36726098, 2023). "Fourth, although previous studies have used a similar sample size to explore the associations between the FKBP5 gene and depressive symptoms or depression, the sample size in the present study is relatively small, which may imply insufficient statistical power these findings." (PMID 34753443, 2021).
depression (continued). "Interestingly, among these were two genes involved in stress signalling and depressive disorders, namely Fkbp5 (encoding FK506 binding protein 5 (FKBP5), a regulator of glucocorticoid receptor (GR) activity) and Adrb1 (encoding the beta-1 adrenergic receptor (β1-AR))." (PMID 33723234, 2021). "Furthermore, some clinical studies have suggested that polymorphisms of FKBP5 gene could be used as a biological indicator for the vulnerability and antidepressants responsiveness to major depression." (PMID 28579944, 2017). "In addition, Fkbp5 is also linked to treatment response in depression." (PMID 23733890, 2013). "Single nucleotide polymorphisms (SNPs) in the FKBP5 gene associate with increased recurrence of depressive episodes, increased susceptibility to post-traumatic stress disorder, bipolar disorder, attempt of suicide, and major depressive disorder in HIV patients." (PMID 21935478, 2011). "PTSD, depression, and alcohol use phenotypes associate with gene variants of FKBP prolyl isomerase 5 (FKBP5), a chaperone modulator of glucocorticoid receptors (GR)." (PMID 41567824, 2026). "A study analyzing the effects of both the CMS protocol and antidepressant treatment on the expression of Fkbp5 and GR in a rat model of depression showed similar differences between mRNA and protein levels." (PMID 40309821, 2025). "Although the link between the FKBP5 gene and trauma has been consistently reported in major depressive disorder and post-traumatic stress disorder, few studies have examined these mechanisms in SCZ and BD or specifically related to SA." (PMID 41300231, 2025). "Considering the role of FKBP5 in regulating the GR and stress response function, previous studies analyzed its expression in animal models of depression." (PMID 40309821, 2025). "In depressive patients, a previous study found that antidepressant treatment decreased FKBP5 expression in peripheral blood cells, highlighting the link between the expression of the co-chaperone and depression." (PMID 40309821, 2025). "The overexpression of FKBP5 correlated with depression-like symptoms in rat models of depression, along with differential expression of microRNAs (miRNAs) involved in Fkbp5 regulation, such as miR-511-5p." (PMID 40309821, 2025). "All FKBP5 CpG units, as well as average CpG, were however negatively correlated with previous psychological treatment or history of depression (ranging from rs = –0.19 to –0.25, p < 0.01)." (PMID 39257475, 2024). "Several preclinical studies with models of depression or anxiety have consistently observed protective effects of FKBP5 knock-out or knock-down on HPA axis function or stress-coping behavior." (PMID 37581323, 2024). "Depression is characterized by concurrent higher FKBP5 mRNA expression and lower GR levels, resulting in GR resistance." (PMID 38609904, 2024). "Childhood maltreatment is an important risk factor for adult depression and has been associated with changes in the hypothalamic pituitary adrenal (HPA) axis, including cortisol secretion and methylation of the FKBP5 gene." (PMID 38338761, 2024). "We examined individual differences in the DNA methylation patterns within the GR receptor NR3C1 and the FKBP5 gene in order to characterize epigenetic markers of personality vulnerability to depression, resilience, and perinatal depressive symptoms." (PMID 39257475, 2024). "This suggests the potential for studying the FKBP5 gene in relation to depression, especially in subpopulations such as those who have experienced childhood trauma." (PMID 38609904, 2024). "FKBP5 rs1360780 T+ was significantly correlated with major depression, according to another meta-analysis finding." (PMID 37051166, 2023). "Changes in DNA methylation of the FK506 binding protein 5 (FKBP5) gene can modulate stress response, which is closely related to depression." (PMID 38249586, 2023).
depression (continued). "Epigenetic changes at the human FKBP5 locus have previously been implicated in PTSD and depression resulting from childhood trauma." (PMID 37525888, 2023). "This provides evidence for the interaction between FKBP5 gene variation and environmental stressors in adolescent depression." (PMID 38249586, 2023). "More studies on the youth population are needed to verify the relation between altered FKBP5 expression and the treatment outcome in adolescent depression." (PMID 34590201, 2023). "A large number of studies have focused on FKBP5 and NR3C1 and OXT gene, broadly associated with stress social and emotional behavior, respectively, and found a consistent response to ELS and depression." (PMID 36517640, 2023). "Our study focused on the relationship between FKBP5 SNPs and depression comorbidity in patients with MAUD, which commonly co-occurs and has a bad prognosis." (PMID 37051166, 2023). "This study aimed to investigate associations between anxiety/depression/chronic pain and oral health-related quality of life (OHRQoL)/happiness/polymorphisms in the COMT, HTR2A and FKBP5 genes in Brazilian adolescents." (PMID 36834016, 2023). "Early trauma, BPD symptoms, depression symptoms, emotional regulation, mentalization, and decrease in FKBP5 methylation." (PMID 37724239, 2023). "Both FKBP5 and Akt are involved in the regulation of depression via dendritic modulation, so Akt and other genes in the network were specifically interrogated." (PMID 38201293, 2023). "The GR target gene FKBP5 emerged as a significant player in depression originally inspired by the inhibitory action of its protein FKBP51 on GR." (PMID 36203007, 2023). "FKBP5 SNPs are highly correlated with depression development and responsiveness to antidepressant drug treatment." (PMID 37051166, 2023). "Given that both MAUD and depression are associated with HPA axis dysregulation, does FKBP5 SNP affect depression susceptibility in individuals with MAUD?" (PMID 37051166, 2023). "In conclusion, FKBP5 is involved in sex differences of ELS-induced depression through regulating sex hormone receptor activity." (PMID 35663561, 2022). "The role of FKBP5/Ptg-10 in stress-related conditions like post-traumatic stress disorder and depression was established in previous studies." (PMID 36430579, 2022). "Based on sex-dependent correlations between FKBP5 levels and depression and anxiety scores as well as with nadir cortisol levels, FKBP5 was suggested as a female-specific biomarker for prolonged cortisol load and the associated risk of psychiatric disorders." (PMID 35449298, 2022). "A significant overrepresentation of the FKBP5 TT and TC genotypes compared to the CC genotype has been revealed in individuals presenting with major depression." (PMID 35205209, 2022). "It is found that hippocampal and prefrontal GR expression was reduced, and FKBP5 was elevated in adolescent chronic stress depression model animals." (PMID 36297314, 2022). "We also included depression-related covariates in our analysis, and the results indicate that the percentage of DNA methylation at one site within FKBP5 remained significantly lower in the persistent DS group than in the healthy control group." (PMID 36451133, 2022). "Another study which focused on the relationship between FKBP5 SNPs and PTSD reported that the rs9470080 TT genotype carriers had a higher risk of developing high co-occurring PTSD and depression symptoms than the C allele carriers." (PMID 35787810, 2022). "One of our recent study also reported the significant association between FKBP5 gene variations and the risk of CAD comorbid depression in a north Chinese population." (PMID 34178482, 2021). "The upregulation of FKBP5 expression has been observed not only in stress exposure and glucocorticoid stimulation but also in melanoma, viral infection, depression, and some other diseases." (PMID 33959663, 2021).
depression (continued). "The results not only support previous findings linking FKBP5 to depression, but also provide the first evidence linking FKBP5 to serotonin." (PMID 33408739, 2020). "The current study proposed a remarkable association between FKBP5 gene variations and the risk of comorbid CAD and depression in a Northern Chinese population." (PMID 32547886, 2020). "It was shown that being a victim of violence during pregnancy not only increases the risk of depression and anxiety symptoms in women after childbirth but is also associated with changes in the methylation level of NR3C1 and FKBP5." (PMID 32373361, 2020). "The exact role of FKBP5 in the risk for CHD and in the association of CHD with depression as well as the underlying pathophysiological mechanisms should be analyzed in further studies." (PMID 32860562, 2020). "In recent years, the FKBP5 gene has gained increased scientific interest regarding the genetic vulnerability to depression." (PMID 32860562, 2020). "The current study found a remarkable association between FKBP5 gene variations and the risk of comorbid CAD and depression in a north Chinese population." (PMID 32547886, 2020). "The exact role of FKBP5 gene polymorphisms in the pathogenesis of comorbid CAD and depression requires further investigation." (PMID 32547886, 2020). "Another study evaluated the interactions among three selected FKBP5 single nucleotide polymorphisms and objectively recorded ELS and self‐reported early life stress (ELS) related to depression symptoms in midlife." (PMID 32951353, 2020). "In fact, several research groups have consistently observed protective effects of FKBP5 knock-out or knock-down on stress-coping behavior and stress endocrinology in preclinical models of depression and anxiety." (PMID 30890970, 2019). "Genetic variations in the FKBP5 gene were shown to be associated with the regulation of the HPA axis, with increased depression recurrence and rapid antidepressant treatment response." (PMID 30678080, 2019). "While we observed main effects of sex, age, body mass index, smoking, and depression symptoms on FKBP5 methylation levels, only the functional FKBP5 SNP (rs1360780) moderated the dynamic changes following DEX." (PMID 31122292, 2019). "FKBP5 has been reported to be one of the biomarkers for stress-response and for effects of antidepressant action in patients with depression." (PMID 30042304, 2018). "FKBP5 has been identified as a candidate gene for major depressive disorder stress-related conditions because it interacts with the HPA axis and plays a role in the regulation of neurobiological stress responses." (PMID 30533439, 2018). "Emerging evidence points to the importance of FKBP5 in the development of stress-related mental disorders such as depression, anxiety disorders, and PTSD." (PMID 28393267, 2017). "In line with a role in aging, elevated levels of FKBP5 transcripts have been correlated with shorter telomere length in depression." (PMID 29206196, 2017). "Hit one represents polymorphisms in the AR, BDNF, 5HTTLPR, FKBP5, and NR3C1, which independently increase the risk of developing depression, AUDs, and suicidal behavior in men." (PMID 28096796, 2016). "A 10% higher methylation rate of FKBP5 intron 7 for individuals with a lifetime history of major depression compared to healthy controls was found." (PMID 28096796, 2016). "FD induced elevation of FKBP5 and suppression of BDNF, which are often linked with the improvement of anxiety disorder, depression, and post-traumatic stress disorder." (PMID 24632812, 2014). "Single nucleotide polymorphisms (SNPs) in the FK506 binding protein 5 (FKBP5) gene combine with traumatic events to increase risk for post-traumatic stress and major depressive disorders (PTSD and MDD)." (PMID 25191701, 2014). "In this same study, there was also a significant association between the chaperone FK506 binding protein 5 (FKBP5) rs1360780 SNP and depression in all AD patients." (PMID 25133184, 2014).